NXPH3 (neurexophilin 3)
Description:
May be signaling molecules that resemble neuropeptides. Ligand for alpha-neurexins (By similarity).
Synonyms: NPH3
Tractability: Antibody: UniProt places it where antibodies can reach, with high confidence; UniProt predicts a signal peptide or a membrane-spanning region; its Gene Ontology location is reachable by antibodies, with medium confidence. PROTAC: ubiquitination databases record sites on it.
Gene: Protein-coding gene on chromosome 17 (49,575,871 to 49,583,827, forward strand). Ensembl gene ENSG00000182575.
Subcellular location: Secreted
Subcellular location (Human Protein Atlas): Vesicles; Mitotic spindle; Predicted to be secreted
Gene Ontology:
Molecular function: signaling receptor binding
Biological process: neuropeptide signaling pathway
Cellular component: extracellular region
Genetic constraint (gnomAD): Loss-of-function variants: 7 observed, 18.48 expected, observed/expected ratio (o/e) 0.38, 90% interval 0.21 to 0.71. The synonymous counts are far from expectation, so gnomAD's model fits this gene poorly and the ratio says little. Missense variants: 282 observed, 344 expected, observed/expected ratio (o/e) 0.82, 90% interval 0.74 to 0.9. Synonymous variants: 101 observed, 140.42 expected, observed/expected ratio (o/e) 0.72, 90% interval 0.61 to 0.85.
Homologues: Orthologues: macaque NXPH3 (98% identical), dog NXPH3 (97% identical), mouse Nxph3 (96% identical), rat Nxph3 (96% identical), guinea pig NXPH3 (96% identical), chimpanzee NXPH3 (96% identical), pig NXPH3 (94% identical), rabbit NXPH3 (88% identical), tropical clawed frog nxph3 (57% identical), zebrafish nxph3 (27% identical). Paralogues in human: NXPH1 (50% identical), NXPH2 (48% identical), NXPH4 (41% identical).
Diseases named in the same sentence as NXPH3 in open-access papers:
NXPH3 is named in the same sentence as 9 diseases in open-access papers, as found by Europe PMC text mining. Sharing a sentence is not in itself a finding about the gene and the disease. The quoted sentences say what the papers report.
degenerative joint disease (1 paper, 2023). "The CALCOCO2 and NXPH3 genes, which are involved in degenerative joint disease in humans, have been discovered in a Soviet heavyweight at ECA11." (PMID 37510415, 2023).
lipodystrophy (1 paper, 2022). A congenital or acquired disorder characterized by abnormal loss or redistribution of the adipose tissue in the body. "Associated with metabolism pathways are DEGs related to metabolic syndromes like maturity-onset diabetes of the young 6 (NEUROD1), Sjogren-Larsson Syndrome (NXPH3), lipodystrophy (CAV1), and Rett Syndrome (GRID1)." (PMID 35883433, 2022).
cancer (2 papers, 2011 to 2022). A tumor composed of atypical neoplastic, often pleomorphic cells that invade other tissues. "Neurexophilin-3, a postulated alpha-neurexin ligand, has never been implicated in cancer, to our knowledge." (PMID 21364760, 2011).
NXPH3 also shares sentences with these, for which no sentence is quoted: maturity-onset diabetes of the young 6 (1 paper); metabolic syndrome (1); Rett syndrome (1); schizophrenia (1); Sjogren-Larsson syndrome (1); tumour (1).